AFP (alpha fetoprotein)
Diseases named in the same sentence as AFP in open-access papers (continued):
Sharing a sentence is not in itself a finding about the gene and the disease.
liver cirrhosis (continued). "In total, 147 patients undergoing liver transplantation were enrolled from our hospital, including liver cirrhosis patients (LC, n=25), AFP negative HCC patients (NEG, n=44) and HCC patients with AFP over 20 ng/mL (POS, n=78)." (PMID 36845695, 2023). "In contrast, older age, male, liver cirrhosis, alcoholic liver disease, tumor differentiation, bile duct invasion, surgical margin, serum PIVKA-II level, or serum AFP level were not prognostic markers for HCC recurrence." (PMID 37285077, 2023). "By expert opinion, HCC surveillance with abdominal US with or without serum AFP levels twice per year is recommended for patients with lean NAFLD and clinical indicators consistent with liver cirrhosis." (PMID 37627125, 2023). "It is reported that only 60%–70% of total HCC patients have elevated AFP levels, and nonspecific increases are also observed in non-HCC diseases such as chronic hepatitis or liver cirrhosis." (PMID 35173766, 2021). "A total of 925 AFP‐negative patients, including 235 HCC patients, 213 chronic hepatitis (CH) patients, and 218 liver cirrhosis (LC) patients, as well as 259 healthy controls were enrolled in this study." (PMID 34145988, 2021). "Here, serum N-linked intact glycopeptides with molecular weight (MW) of 40–55 kDa were analyzed in a discovery set (n = 40) including AFP-negative HCC and liver cirrhosis (LC) patients using label-free quantification methodology." (PMID 33889548, 2021). "Positive LC3 expression is related to tumor size but not to gender, age, number of tumors, HBsAg, liver cirrhosis, TNM stage, AFP, vascular invasion and histological grade." (PMID 32157437, 2020). "A total of 199 healthy controls and 515 AFP-negative patients were enrolled in this study, including 180 HCC inpatients, 151 liver cirrhosis (LC) patients, and 184 chronic hepatitis (CH) cases." (PMID 32190001, 2020). "Fattovich followed 384 patients with compensated liver cirrhosis due to HCV infection without HCC at enrollment, of which 200 patients had data regarding AFP levels." (PMID 32341704, 2020). "The results of our study show that increased LC3 expression is related to size of tumor, but not to gender, age, number of tumor, liver cirrhosis, HBsAg, TNM stage, alpha fetoprotein, vascular invasion and histological grade." (PMID 32157437, 2020). "On the contrary, CLCA4 expression had no significance with gender, age, AFP level, HBsAg, gamma-glutamyltransferase (GGT), liver cirrhosis, tumor number, satellite nodule, tumor differentiation and BCLC stage (all P > 0.05)." (PMID 30312171, 2018). "Comparison of liver cirrhosis patients with and without HCC (n = 55) revealed significantly high AFP (p < 0.001) and IL-6 (p < 0.001) levels." (PMID 29963457, 2018). "Age, sex, ECOG PS status, AJCC stage, presence or absence of hepatitis, liver cirrhosis, or PVTT, AFP levels, pretreatment CP class, and GTV were not different between the two NLR groups." (PMID 28199977, 2017). "AFP is not HCC specific because elevated serum levels of AFP are also found in other conditions such as pregnancy, hepatitis, and liver cirrhosis." (PMID 24689054, 2014). "Among liver cirrhosis cases without hepatocelluar carcinoma (HCC), AFP is reported to be elevated in 20% and to exceed 100 ng/mL in only 3%." (PMID 24059753, 2013). "In addition, compared to AFP, EV-DLEU2 showed a higher negative rate in the CH and liver cirrhosis groups and a higher positive rate in the HCC group, suggesting that EV-DLEU2 has a good ability to distinguish between HCC and non-HCC patients." (PMID 37095423, 2023). "However, age, sex, tumor size, differentiation, alpha-fetoprotein, HBV DNA, and liver cirrhosis were not significantly correlated with RNF31 expression." (PMID 35869046, 2022). "Finally, due to the nature of cross-sectional studies, the temporal relationship between HO-1 induction (represented as the (GT)n genotype) and liver cirrhosis, as well as GOT/GPT and AFP, is not clarified in this study." (PMID 33916685, 2021).
liver cirrhosis (continued). "Thirty control cases, 55 liver cirrhosis patients without HCC, and 75 liver cirrhosis cases with HCC were evaluated in the current trial; AFP (p < 0.001) and IL-6 (p < 0.001) were found to be significantly higher among HCC cases, as compared with control group." (PMID 29963457, 2018). "In this study, no Epi-HAML case was accompanied with liver cirrhosis, TSC, or elevated plasma AFP." (PMID 30619742, 2018). "Patients with liver cirrhosis or BCLC stage B had a worse prognosis (P = 0.0031 and P=0.0145) and the other conventional clinicopathological features, such as gender, age, AFP levels, HBsAg, ALT, tumor size and tumor number, none of them could predict the DFS." (PMID 29340079, 2017). "However, the sensitivity of LAIR-1 expression as a noninvasive molecular marker in liquid biopsy is accepted for the detection of HCC progression from liver cirrhosis HCV G4-related infection, which opens the door for better screening of AFP-negative HCC transformation." (PMID 36293412, 2022).
liver disease (364 papers, 2007 to 2026). "Multiple factors influence recurrence risk, including tumor size and number, AFP levels, vascular invasion, and underlying liver disease etiology." (PMID 41464773, 2025). "AFP is the most widely used serum biomarker for HCC diagnosis and HCC surveillance using ultrasound and AFP at semiannual intervals is recommended in the American Association for the Study of Liver Diseases (AASLD) guideline." (PMID 40038575, 2025). "In the training cohort, significant differences were observed in the tumor size category, AFP category, Child–Pugh grade, portal hypertension, and blood loss category between the GPR-low and GPR-high groups." (PMID 38773511, 2024). "Combining the imaging aspects with serum biomarkers such as AFP in a patient with a diagnosed liver disease increases diagnostic accuracy." (PMID 38791994, 2024). "It is well known that severe liver disease and advanced tumor stage are associated with elevated AFP levels." (PMID 36831565, 2023). "Advancements in antiviral therapy and the management of underlying liver diseases can also affect the reliability of AFP testing as a screening tool." (PMID 38201578, 2023). "Advanced tumor stage, severe underlying liver disease, viral etiology, and female gender are associated with elevated AFP levels in HCC patients." (PMID 36831565, 2023). "After the IPTW adjustment, the three treatment groups had similar baseline parameters including those deemed to potentially influence treatment selection, such as tumor size and number, AFP, and severity of underlying liver disease." (PMID 36016484, 2023). "Previous studies have shown that female gender, viral etiology, severe underlying liver disease, and advanced tumor stage are independently associated with elevated levels of AFP, findings that are compatible with those of the present study." (PMID 36831565, 2023). "For example, the combination of betaine and propionyl carnitine in the serum can make for a good prediction of liver diseases and can be used as a supplementary diagnosis method for the clinical fatty liver cancer diagnostic marker, alpha-fetoprotein (AFP)." (PMID 36139459, 2022). "As serum AFP levels are often measured as part of the diagnostic workup for neonatal liver disease, we observed several cases of markedly elevated AFP levels in infants who were eventually diagnosed with NPC." (PMID 35455589, 2022). "The American Association for the Study of Liver Disease also recommended that HCC surveillance should be considered positive when the AFP level is greater than 20 ng/mL." (PMID 36140487, 2022). "It is worth noting that MetS-related patients commonly developed HCC with mild underlying liver disease or low serum AFP levels." (PMID 35356224, 2022). "There was no statistical relationship between early TACE refractoriness and age, gender, Child-Pugh class, underlying liver disease, history of resection, initial AFP level, and NLR level." (PMID 33816555, 2021). "The invaded area of the rRPS, maximum tumor size, alpha-fetoprotein (AFP), presence of portal hypertension, and PV/HV branch invasion were significantly associated with OS in the univariate analysis (P < 0.1)." (PMID 33072569, 2020). "Guidelines from American Association for the Study of Liver Diseases (AASLD) stated that the level of AFP exceeding 200 ng/mL was enough for tumor diagnosis." (PMID 32433581, 2020). "Cause of liver disease and tumor characteristics, including AFP level, tumor size and number, and number of local-regional treatments, were similar among groups." (PMID 31469395, 2019). "The most important risk factors for HCC among all etiologies of liver disease were older age, male gender, Hispanic ethnicity, high serum AFP, alkaline phosphatase, and AST/√ALT ratio, and low platelet count and serum albumin." (PMID 30260995, 2018).
liver disease (continued). "As previously documented, the diagnostic yield of AFP for HCC is significantly lower when using a control group including more advanced liver disease patients, which is comparable to this study." (PMID 26986465, 2016). "High AFP levels have also been described in diseases produced by AFP gene mutation, including hereditary persistence of alpha-fetoprotein; inflammatory liver diseases, usually associated with malignant transformation; and germinal cell neoplasms." (PMID 25374730, 2014). "The Italian and the American Association for the Study of Liver Diseases guideline considers an AFP level of ≥200 ng/mL to be diagnostic for HCC." (PMID 22559879, 2012). "According to the American Association for the Study of Liver Diseases, positive AFP for HCC is defined as ≥20 ng/mL; in our study population, 43% of HCC tissues (n = 53 for which AFP levels were available) were positive for AFP." (PMID 22073196, 2011). "Cox regression analyses adjusting for age, sex, race, AFP, Child-Pugh class, liver disease cause, and extrahepatic disease confirmed that overall survival was greater in complete responders compared with other patients when accounting for clinical factors (HR, 0.06; 95% CI, 0.01-0.44)." (PMID 39998829, 2025). "Furthermore, the diagnostic reliability of CA 19-9 and alpha-fetoprotein (AFP) is compromised due to their variable elevation in different liver diseases." (PMID 39286634, 2024). "Consequently, the guidelines established by the American Association for the Study of Liver Diseases in 2010 removed the suggestion of employing AFP as a screening tool for HCC." (PMID 37627215, 2023). "Furthermore, advanced tumor stage and severe underlying liver disease were associated with elevated AFP levels." (PMID 36831565, 2023). "Notably, the dataset includes many known proteins (IL6, IL10, IFNG, CSF3, PDGFB, CD40, and AFP) and novel proteins associated with liver diseases." (PMID 37209815, 2023). "This is because fluctuating levels of AFP in cirrhotic patients can not only indicate HCC development but may also reflect exacerbation of underlying liver disease or flares of HBV or HCV infection." (PMID 37432493, 2023). "Furthermore, advanced tumor stage, severe underlying liver disease, female gender, and viral etiology were associated with elevated AFP in HCC patients." (PMID 36831565, 2023). "Consequently, the EASL and the American Association for the Study of Liver Diseases (AASLD) recommend the use of AFP in combination with ultrasound and other biomarkers for HBV-related HCC diagnosis." (PMID 36363693, 2022). "However, it is still controversial due to the prognostic efficacy of AFP being heavily influenced by patient gender, underlying liver disease, and the severity of HCC." (PMID 35884432, 2022). "Patients may present with acute decompensation of their underlying liver disease, or through routine screening of at-risk populations by ultrasound scanning and measurement of alpha-fetoprotein (AFP) levels." (PMID 35323324, 2022). "Several factors have been identified to be associated with elevated serum AFP in patients with liver disease of chronic hepatitis C other than HCC, such as elevated ALT, decreased platelet count, lower albumin levels, older age, female gender, ethnicity, and advanced fibrosis." (PMID 36016291, 2022). "As both the APAC and GALAD scores are based on the quantification of AFP, it should be noted that fluctuating AFP levels due to flares of viral infection or exacerbation of the underlying liver disease may potentially influence their outcome." (PMID 34362181, 2021). "Furthermore, this research revealed that PIVKA‐II was less affected by the patients with HBV‐related liver disease, showing its superior diagnostic efficacy than AFP." (PMID 34590755, 2021).
liver disease (continued). "Within 2 years of diagnosis, the combination of OPN and alpha-fetoprotein (AFP) best predicted HCC development, suggesting that measuring OPN and AFP could identify high-risk groups independently of a liver disease." (PMID 34440210, 2021). "AFP is widely recognized as a prognostic predictor of survival for patients with HCC undergoing LT based on studies of patients with heterogeneous underlying causes of liver disease." (PMID 33134370, 2020). "Importantly, in the HCC patients with small tumor sizes (<5 cm), our triplex miRNA and Mir@AFP panels also showed a greater diagnostic performance in distinguishing HCC from the other HBV-related liver diseases, especially from patients with LC." (PMID 29672637, 2018). "Multivariate analysis test suggested that preoperatively elevated AFP above 200 ng/mL, existence of macrovascular invasion, having underlying liver diseases due to alcohol abuse were associated with poor survival in addition to strong PDGFRα positivity on tumor sites." (PMID 28465473, 2017). "Concordant with others, the authors observed that patients with cHCC-CC were more likely to have higher serum AFP levels, background liver disease, were more often males and <60 years of age, compared to those with ICC." (PMID 41594290, 2026). "Assessed outcomes included survival, biochemical, hematologic, AFP, metabolic and cardiovascular parameters, progression to advanced liver disease (ALD), synthetic function, and metabolic markers over 1, 5, and 10 years." (PMID 40872510, 2025). "Despite its limitations, AFP continues to serve as a practical and widely adopted biomarker in assessing liver disease progression and surveillance for HCC." (PMID 41142526, 2025). "In the most recent study, the diagnostic performance of a biomarker panel including AFP, AFP-L3, DCP, and CA 19-9 was evaluated in liver diseases." (PMID 40723883, 2025). "Their liver and kidney function tests as well as tyrosine, SA, and AFP levels were supraphysiological, and histological analysis confirmed liver disease." (PMID 40143050, 2025). "AFP-L3% and AFP can be used for the risk assessment and screening of HCC in high-risk patients with liver disease." (PMID 40563863, 2025). "Assessed outcomes included survival, biochemical, hematologic, AFP, metabolic and cardiovascular parameters, advanced liver disease (ALD), synthetic function, and metabolic markers." (PMID 40732362, 2025). "The degree of fucosylation of AFP was proved to be beneficial for distinguishing HCC from benign liver diseases when the AFP concentration was lower than 1000 ng/mL, which is insufficient for this purpose." (PMID 40821120, 2025). "Recently, PIVKA-II proposed to serve as a complementary or alternative diagnostic tool to AFP for HCC, while its diagnostic performance in detecting early-stage HCC was notably influenced by the underlying liver disease etiology." (PMID 40241895, 2025). "AFP levels can be influenced by various factors other than tumor progression, such as liver function status, presence of other liver diseases, or even individual physiological variations." (PMID 39767676, 2024). "AFP is typically produced at low levels in healthy individuals and plays a crucial role in liver diseases, particularly in primary HCC." (PMID 39021573, 2024). "All these results suggest that LC-SPIK exhibits significantly better performance in the detection of HCC than AFP in all etiologies of liver diseases." (PMID 38611638, 2024). "Preoperative clinical factors, including tumor size and number, gender, age, AFP level, ALBI grade, and portal hypertension status, were independently associated with long‐term outcomes, consistent with prior studies." (PMID 36016484, 2023). "Secondly, the clinical information of the samples was limited, and some essential factors for determining patient prognosis, such as alpha-fetoprotein, ascites, portal hypertension, and postoperative complications, were missing." (PMID 37680641, 2023).